ADAM12 (ADAM metallopeptidase domain 12)
Diseases named in the same sentence as ADAM12 in open-access papers (continued):
Sharing a sentence is not in itself a finding about the gene and the disease.
glioma (13 papers, 2016 to 2025). A benign or malignant brain and spinal cord tumor that arises from glial cells (astrocytes, oligodendrocytes, ependymal cells). "In another report, miR-135-5p was shown to inhibit cell proliferation by targeting the ADAM12 gene in glioma cells." (PMID 40728965, 2025). "Among them, ADAM9, ADAM12, ADAMTS7, ADAMTS9, and ADAMDEC1 were the proteases where increased expression associated with poorer prognosis of glioma patients." (PMID 36172139, 2022). "It has been proven that ADAM12, ADAMTS4 and 5 are implicated in the proliferation and invasion of glioma cells." (PMID 34638718, 2021). "Additionally, recent studies have shown that SP1 can induce the expression of LINC01614, thereby enhancing the malignant development of gliomas through the miR‐383/ADAM12 pathway." (PMID 40735832, 2025). "Additionally, SP1 can induce LINC01614 expression to enhance the malignant development of gliomas via the miR-383/ADAM12 pathway." (PMID 39596660, 2024). "In addition to ADAM9, several other members of the ADAM family have also been implicated in tumor growth and invasiveness of gliomas, such as ADAM10, ADAM12 and ADAM17." (PMID 27571068, 2016). "Similarly, low editing of miR-589 in glioma was reported to change its specificity from disintegrin and metalloproteinase domain-containing protein 12 (ADAM12), a primary target of miR-589, towards protocadherin 9 (PCDH9), thereby promoting cell migration and invasion." (PMID 31835747, 2019). "In glioma, the upregulation of LINC01614 by SP1 promoted cancer progression by regulating the miR-383/ADAM12 axis." (PMID 38655053, 2024). "ADAM12 and ADAMDEC1 have an obvious impact on the prognosis of glioma patients through comprehensive analysis including overall survival and ADAMs expression levels." (PMID 36172139, 2022). "Another study reported that, through the regulation of ADAM12, SP1-mediated upregulation of lncRNA LINC01614 functions as a ceRNA for miR-383, thereby facilitating glioma progression." (PMID 33889541, 2021).
breast tumor (11 papers, 2014 to 2021). "ADAM12 is induced during epithelial-to-mesenchymal transition, a feature associated with claudin-low breast tumors, which are enriched in cancer stem cell (CSC) markers." (PMID 28148288, 2017). "Therefore TAK1 activity is indeed strongly associated with ADAM12 expression in breast tumors." (PMID 30753595, 2019). "We then stratified the breast tumor samples based on ADAM12 mRNA levels, and compared the high-ADAM12 group (highest decile for ADAM12 expression) to the low-ADAM12 group (lowest decile) and to normal tissue." (PMID 30753595, 2019). "To investigate the physiological relevance of these observations, we next analyzed the expression of ADAM12 in 79 breast tumor samples." (PMID 26407179, 2015). "NSD3 directly interacted with EZH2 and RNA polymerase II to stimulate H3K36 methylation-dependent transcriptional activation of NOTCH receptor cleavage-associated genes (including Adam12, DLL4, and Notch3), thereby activating Notch signaling to promote breast tumor progression." (PMID 34615858, 2021). "Certainly, the mRNA expression of TWIST1 and ADAM12 is strongly correlated in human breast tumors, and the TWIST1 transcription factor promotes tumor invasion and metastasis by inducing epithelial-mesenchymal transformation and invadopodia-mediated degradation of the extracellular matrix." (PMID 34604068, 2021). "This resulted in near-perfect segregation of normal, ADAM12-low, and ADAM12-high breast tumors." (PMID 30753595, 2019). "Indeed, recently, it has been reported that ADAM12 was elevated in claudin-low tumor and a part of stromal, mammosphere, and EMT gene signatures, which were all associated with breast tumor-initiating cells (BTICs)." (PMID 28852196, 2017). "When the breast tumors were stratified by subtype, the analysis revealed that not only triple-negative tumors contained high-ADAM12 and low-TAK1 samples, but the other groups did as well." (PMID 30753595, 2019).
prostate carcinoma (10 papers, 2005 to 2023). A carcinoma that arises from epithelial cells of the prostate gland. "Consistent with increased resistance mechanisms, stratification of human prostate cancer by ADAM12 expression further correlated with the Gleason score, which identifies high-grade tumors at high risk of recurrence." (PMID 37798557, 2023). "A positive correlation between basigin and a disintegrin and metalloproteinase (ADAM)-12 in serum from prostate cancer patients has been reported." (PMID 31013576, 2019). "Moreover, we have identified that TMEFF2 is also a novel substrate for other proteases implicated in prostate cancer, including two ADAMs (ADAM9 and ADAM12) and the type II transmembrane serine proteinases (TTSPs) matriptase‐1 and hepsin." (PMID 28762604, 2018). "Additionally, ADAM12 regulates prostatic cancer cell invasion through the NF-κB signaling pathway." (PMID 33923541, 2021). "A slow-cycling YFP+Ki-67– cells were also abundant at the interface of normal tissue and SV40+ prostate cancer cells that metastasized to the liver and bone in TRAMP × ADAM12-tTA-CreYFP mice, further suggesting a role for ADAM12+ MSCs in the metastatic niche." (PMID 37798557, 2023). "A recent study showed a significant correlation between serum levels of ADAM12 and BSG from prostate cancer patients." (PMID 31013576, 2019). "Overexpression of ADAM species is known in tumor cell lines, for example, ADAM10, ADAM12 and ADAM15 in hematological malignant tumor cell lines, and ADAM9, ADAM10, ADAM15 and ADAM17 in prostate cancer cell lines." (PMID 16277668, 2005). "ADAM12 was also reported as a novel regulator in tumor angiogenesis via STAT3 signaling and as a prognostic marker for various cancers, including breast and prostate cancers." (PMID 34121340, 2021).
cardiac hypertrophy (9 papers, 2013 to 2025). "In our previous study, loss of ADAM12 in mice caused severe cardiac hypertrophy and dysfunction after transverse aortic constriction." (PMID 38351156, 2024). "Loss of ADAM12 or 17 mediated cardiac hypertrophy via increased integrin B1 levels that result in overactivation of integrin-FAK signaling." (PMID 33400052, 2021). "Adam12 has been implicated in the development of cardiac hypertrophy and elevated expression of Adam12 is observed in human and rodent cardiac tissue during hypertrophic obstructive cardiomyopathy and agonist-induced cardiac hypertrophy." (PMID 24586524, 2014). "ADAM12 is also implicated in processes of excessive growth, such as cardiac hypertrophy." (PMID 37662558, 2023). "ADAM12 was initially identified as a regulator of heart function because chemical antagonism of ADAM12 provides potent inhibition of cardiac hypertrophy." (PMID 37079380, 2023). "In ADAM22, as well as in ADAM12 knockout mice, cardiac hypertrophy was aggravated under pressure overload." (PMID 33400052, 2021). "Moreover ADAM12, a member of the same subfamily and closely related to ADAM33, is involved in development of cardiac hypertrophy that leads to sudden cardiac death." (PMID 23861802, 2013).
colorectal cancer (9 papers, 2020 to 2026). A primary or metastatic malignant neoplasm that affects the colon or rectum. "Moreover, ADAM12 levels in serum have recently been linked to patient prognosis in colorectal cancer with an especially strong correlation to metastatic rectal cancer." (PMID 37495855, 2023). "Here, we report on a serum marker for stromal activation, A Disintegrin and Metalloprotease 12 (ADAM12) in colorectal cancer (CRC)." (PMID 35413826, 2022). "The aim of the current study was to evaluate the impact of ADAM12 on cancer progression, prognosis, and therapeutic targets in colorectal cancer (CRC)." (PMID 33923541, 2021). "Given the increase in endothelial cells and a tendency toward increased vessel number in A12−/− tumors, we hypothesize that ADAM12 sheds anti-angiogenic factors from the surface of the colorectal cancer cell surface." (PMID 37495855, 2023). "Therefore, we evaluated the role of ADAM12 in colorectal cancer (CRC) progression and prognosis, and elucidated whether targeted downregulation of ADAM12 could lead to therapeutic sensitization." (PMID 33923541, 2021).
bladder cancer (8 papers, 2010 to 2022). "Apart from that, urinary level of ADAM12 was also found to be elevated in patients with bladder cancer." (PMID 33507683, 2021). "In particular, ADAM12 is overexpressed in various pathological conditions, including adenocarcinoma and breast and bladder cancer, as well as several fibrotic diseases." (PMID 27128408, 2016). "We, and others previously showed that ADAM12 expression was markedly upregulated in different cancers, and that the level of ADAM12 in urine from breast and bladder cancer patients correlated with disease status and stage." (PMID 22662180, 2012). "In the small number of cases studied, urinary ADAM12 levels decreased following surgical removal of the bladder cancer but increased again with recurrent disease." (PMID 21906355, 2011). "Similarly, we detected bands of a size corresponding to shed BSG in a Western blot of sera from five bladder cancer patients, which we previously reported exhibit high levels of soluble ADAM12 in the circulation." (PMID 31013576, 2019). "Indeed, measurement of ADAM12 appeared to be a more sensitive diganostic marker for bladder cancer that standard cytology." (PMID 21906355, 2011). "This latter finding suggests that measurement of urinary ADAM12 may be suitable for monitoring patients with bladder cancer." (PMID 21906355, 2011). "Interestingly, in the urine of bladder cancer high levels of ADAM12 were detectable, suggesting ADAM12 as a promising biomarker for bladder cancer." (PMID 20070888, 2010).
colon carcinoma (8 papers, 2013 to 2023). "Analysis of ADAM12 mRNA levels in human SW480 colon cancer cells irradiated with a dose of 10 Gy showed a significant upregulation at both 24 and 48 h post-irradiation." (PMID 37495855, 2023). "Compared with the corresponding normal tissue samples, ADAM12 overexpression was observed in colon cancer tissues, including COAD, colon mucinous adenocarcinoma, rectal adenocarcinoma, and cecum adenocarcinoma." (PMID 34604068, 2021). "We also conclude that TAK1 activity is a strong positive determinant of ADAM12 expression in lung, breast, and colon cancer." (PMID 30753595, 2019). "Moreover, conditioned medium from ADAM12−/− colon cancer cells led to increased tube formation when added to endothelial cell cultures." (PMID 37495855, 2023). "After confirming that ADAM12 is upregulated by irradiation in colon cancer cell lines similar to tumor tissues in our cohort, we tested whether the loss or gain of ADAM12 affects the cells’ radiosensitivity." (PMID 37495855, 2023). "We also attempted to induce ADAM12 expression in the murine MC38 colon cancer cell line with ionizing radiation, but our analysis showed that MC38 cells do not express ADAM12 in vitro and we could not induce its expression using ionizing radiation." (PMID 37495855, 2023). "Likewise, we observed increased ADAM12 mRNA expression in the murine CT26 colon cancer cell line at 14 and 24 h, following 5 Gy irradiation." (PMID 37495855, 2023). "In addition to the irradiation-induced upregulation of ADAM12 in both colon cancer cells in vitro and in rectal tumor tissue, our study showed a correlation of ADAM12 expression to patient disease-free survival following RT." (PMID 37495855, 2023). "To unravel the mechanism by which ADAM12 affects tumor progression following RT, we used human SW480, as well as mouse CT26 and MC38 colon carcinoma cell lines, as model systems." (PMID 37495855, 2023). "Firstly, we validated that ADAM12 expression is upregulated in SW480 and CT26 colon cancer cell lines following irradiation." (PMID 37495855, 2023). "The results also supported that SPP1, COL11A1, ADAM12, and INHBA expressions were significantly higher in colon cancer tissues compared to that of the normal tissues in accordance with our previous study." (PMID 30746900, 2019). "While we found no cell-autonomous effects of ADAM12 on the response of colon cancer cells to irradiation in vitro, depletion of ADAM12 expression markedly reduced the tumor growth of irradiated cancer cells when subcutaneously transplanted in syngeneic mice." (PMID 37495855, 2023). "We found that SPP1, VIP, COL11A1, CA2, ADAM12, INHBA could provide great significant prognostic value for colon cancer." (PMID 30746900, 2019). "Thus, our findings indicate that ADAM12 regulates the response of colon cancer cells to RT indirectly by affecting the TME rather than modulating the cell-autonomous radiosensitivity." (PMID 37495855, 2023).
glioblastoma (6 papers, 2005 to 2025). The most malignant astrocytic tumor (WHO grade IV). "ADAM12 is highly expressed in glioblastoma multiforme, where it is linked to shedding of HB-EGF." (PMID 33946495, 2021). "In the context of de novo glioblastoma, a highly aggressive brain cancer, ADAR2-mediated editing of miR-589-3p results in a shift from its regulation of the tumor suppressor PCDH9 to the modulation of ADAM12, effectively impeding glioblastoma invasion." (PMID 38911375, 2024). "Editing within miR-589–3p retargets the miRNA from the protocadherin PCDH9 to the metalloprotease ADAM12, which is involved in glioblastoma cell invasion." (PMID 34282776, 2021). "ADAM12 was selectively overexpressed in the highly malignant glioblastomas and appeared to play a key role in the tumor cell proliferation through shedding of heparin-binding epidermal growth factor." (PMID 16277668, 2005). "Therefore, we validated by qRT-PCRs the expression of both ADAM12 and PTX3 in siADAR2 glioblastoma cells (A172 and U87MG)." (PMID 36009036, 2022).
liver cancer (6 papers, 2014 to 2025). An epithelial or non-epithelial malignant neoplasm that arises from the liver. "Kaplan–Meier and Cox regression analyses revealed that ADAM12 gene expression is an independent risk factor influencing the prognosis of patients with liver cancer." (PMID 35459884, 2022). "Liver fibrosis and cirrhosis caused by chronic hepatitis B are important risk factors for liver cancer; therefore, ADAM12 is closely related to liver injury and liver cancer." (PMID 35459884, 2022). "Moreover, we clarified the biological pathway and mechanism of the ADAM12 gene implicated in the regulation of the occurrence and development of liver cancer via gene enrichment analysis (GSEA) and immune cell invasion analysis." (PMID 35459884, 2022). "Gene expression studies of HCC reported that the ADAM12 gene is highly expressed in HCC tissues and associated with poor prognosis, suggesting a potential biomarker for liver cancer diagnosis." (PMID 39858049, 2025). "To further explore the specific reasons that the ADAM12 gene affects the proliferation and viability of liver cancer cells, we carried out cell cycle experiments." (PMID 35459884, 2022). "In this study, we evaluated the contribution of ADAM12 gene expression to the prognosis of liver cancer using liver cancer samples obtained from the TCGA database." (PMID 35459884, 2022). "In the present study, the expression level of the ADAM12 gene was significantly and positively correlated with tumour size and pathological stage, indicating that the ADAM12 gene can potentially be used as an indicator of liver cancer stage." (PMID 35459884, 2022). "The high expression of the ADAM12 gene in liver cancer tissue significantly and positively correlated with T stage, pathological stage, and residual tumour." (PMID 35459884, 2022). "To verify the bioinformatics analysis results and determine the correlation between ADAM12 gene expression and liver cancer, we first compared the expression of ADAM12 in cancer tissues and adjacent tissues taken from liver cancer patients." (PMID 35459884, 2022). "Subsequently, Wilcoxon signed-rank test was performed to analyse the paired sample data of ADAM12 expression in 50 cases of liver cancer and adjacent tissues." (PMID 35459884, 2022). "We analysed the integrated data and discovered that the expression level of the ADAM12 gene in primary liver cancer tissues was significantly higher than that in paracancerous tissues." (PMID 35459884, 2022). "Overall, this research revealed that high ADAM12 gene expression implies a poor prognosis for patients with primary liver cancer." (PMID 35459884, 2022). "The results showed that the ADAM12 gene was significantly and highly expressed in liver cancer tissue." (PMID 35459884, 2022). "The results showed that low ADAM12 gene expression blocked the transition of liver cancer cells from the G1 phase to the S phase." (PMID 35459884, 2022). "The results of this study showed that ADAM12 was positively correlated with the expression of TGF-β (a marker of fibrosis) in liver cancer." (PMID 35459884, 2022). "Previously, it was shown that ADAM12 inhibits apoptosis by regulating Akt and mitogen-activated protein kinase signaling pathways in breast and liver cancer cells." (PMID 33923541, 2021). "Furthermore, the Kaplan–Meier Plotter database was used to analyse the clinical significance of ADAM12 gene expression in the prognosis of liver cancer." (PMID 35459884, 2022). "Notably, the ADAM12 gene is a binding partner of the activated protease C receptor during liver fibrosis, and both ADAM12 and protease C are highly expressed in liver cancer and liver fibrosis." (PMID 35459884, 2022). "Notably, the relationship between ADAM12 expression and liver cancer has rarely been reported; however, ADAM12 has been shown to promote liver fibrosis." (PMID 35459884, 2022). "Nonetheless, reports on ADAM12 in primary liver cancer remain rare." (PMID 35459884, 2022).
liver cancer (continued). "Therefore, the effect of ADAM12 expression on hepatic fibrosis implies that ADAM12 might be closely related to the occurrence and development of liver cancer." (PMID 35459884, 2022). "The γ-secretase inhibitor DAPT is a potent inhibitor of the Notch signalling pathway, and therefore, it was added to the cell cultures; however, inhibition of Notch signalling did not change the expression of ADAM12, but it inhibited the proliferation of liver cancer cells." (PMID 35459884, 2022).
Obesity (6 papers, 2007 to 2025). Accumulation of substantial excess body fat. "We have identified two QTL genes, Adam12 and Cdh2, as causal genetic variants for atherogenic diet-induced obesity." (PMID 17653278, 2007). "Notably, due to the single-gene resolution achieved by our GWA scans, we firmly establish two QTL genes, Adam12 and Cdh2, as causal variants for obesity in inbred mice." (PMID 17653278, 2007). "ADAM12 is an active protease in ECM that causes changes in proliferation and differentiation of adipocyte maturation and also in the development of obesity induced by high-fat diet." (PMID 32316129, 2020). "As extraversion is known to be associated with lifestyle, obesity and substance abuse, we deem BDNF to be an interesting candidate gene for extraversion in future studies, along with CRTAC, ADAM12 and RELN." (PMID 26362575, 2016). "Since Adam12 and Cdh2 are the only candadiate gene in each of their QTL regions and further supported by the evidence from knockout and/or transgenic mice, we can safely establish these two QTL genes as casual genetic variants for atherogenic diet-induced obesity in natural inbred mouse populations." (PMID 17653278, 2007). "In particular, ADAM metallopeptidase domain 12 (ADAM12) and cytochrome P450 family 1 subfamily B member 1 (CYP1B1) were found to be upregulated in obesity and their silencing reduced RCC cell invasiveness." (PMID 39806854, 2025).